C1QA (complement C1q A chain)
Diseases named in the same sentence as C1QA in open-access papers (continued):
Sharing a sentence is not in itself a finding about the gene and the disease.
Autoimmunity (7 papers, 2014 to 2025). The occurrence of an immune reaction against the organism's own cells or tissues. "C1QA deficiency is thought to promote autoimmunity by impairing the clearance of apoptotic cells and nuclear antigens, which may cause the generation of autoantibodies." (PMID 41086024, 2025). "In our case, we hypothesized that C1qa knockout mice would lack the ability to clear out cellular debris caused by continuous noise exposure and this would lead to local autoimmunity in the cochlea." (PMID 24804771, 2014). "C1Q deficiency in C1qa-/- mice can be restored by BMT, a clinically important observation in view of the autoimmunity associated with C1Q deficiency." (PMID 39869647, 2025). "Determining the contributions of C1q to immune functions in vivo is challenging due to the increased mortality of C1qa subunit-knockout mice, which succumb to severe autoimmunity resulting from impaired clearance of apoptotic cells." (PMID 35983035, 2022). "Because immunoglobulin extravasation in Tspan12-KODBM; C1qa-KO compound mutant mice may promote autoimmunity, we examined the fundus of mice of all 4 genotypes." (PMID 41086024, 2025). "Indeed, as C1qa−/− mice age they develop multiple apoptotic bodies and autoimmunity compared to WT controls." (PMID 24945405, 2014). "The complement system also plays a crucial role in SLE pathogenesis, particularly components such as C1QA, C1QB, C2, and C3, which are essential for clearing apoptotic debris and immune complexes, thereby reducing autoimmunity and systemic inflammation." (PMID 39717551, 2024). "The finding that these phenotypes were not present in Tspan12-KODBM; C1qa-KO mice suggests that autoimmunity does not develop." (PMID 41086024, 2025).
glioma (7 papers, 2019 to 2024). A benign or malignant brain and spinal cord tumor that arises from glial cells (astrocytes, oligodendrocytes, ependymal cells). "We, therefore, performed a bioinformatics analysis, using Oncomine dataset and UALCAN database in order to assess whether the expression of the genes encoding for the three chains of C1q (C1qA, C1qB, and C1qC) could serve as a potential prognostic marker for gliomas." (PMID 31649675, 2019). "As a result of C activation, high expression of C1QA, C1QB, and C1QC, encoding the three chains of C1q, were observed in gliomas." (PMID 37174113, 2023). "Previous studies have shown that C1q, the first recognition subcomponent of the complement classical pathway, comprises three chains (C1qA, C1qB, and C1qC) and exerts complex effects on tumorigenesis of multiple tumors, including prostate, and ovarian cancer as well as gliomas." (PMID 33014868, 2020). "C1qA, C1qB, and C1qC expression in gliomas in the datasets used in the current study with Oncomine." (PMID 31649675, 2019).
Sepsis (7 papers, 2019 to 2026). Sepsis is defined as life-threatening organ dysfunction caused by a dysregulated host response to infection. "Among the top 40 DEGs analyzed by RNA sequencing of whole hippocampus tissue at day 3 following sepsis induction, we observed up-regulation of C1qa, C1qb, and C1qc encoding for complement factor C1q." (PMID 37235660, 2023). "C1qA deficiency is associated with increased susceptibility to sepsis." (PMID 40426888, 2025). "Reduced expression levels of TNF-α, IL-1α, and C1qA were exhibited in the hippocampus of the berberine treatment group, and attenuated effect of declining neo-neuron, activation of microglia and astrocytes in the hippocampus of mice with sepsis were also found." (PMID 34867376, 2021). "At the same time, we also detected the C1q signaling pathway and found that the expression of C1QC was elevated in the peripheral blood of patients with sepsis, while C1QA had no significant change." (PMID 36845133, 2023).
systemic lupus erythematosus (7 papers, 2017 to 2025). An autoimmune multi-organ disease typically associated with vasculopathy and autoantibody production. "Point mutations in PROA have been associated with increased levels of lupus, whilst further studies have identified C1qA mutations in an African-American pedigree leading to lack of expression and lack of complement activation in these patients." (PMID 40801960, 2025). "For instance, we know about the existence of cases of systemic lupus erythematosus caused by monogenic mutations in the C1qA, B, C, C1R, DNASE1, DNASE1L3, and ACP5 genes, among many other predisposing genetic variations." (PMID 36900420, 2023). "Apoptotic cells are a source of self-antigen and lead to the production of autoantibodies; therefore, C1qa-deficient mice spontaneously develop systemic lupus erythematosus (SLE)-like disease due to the accumulation of apoptotic cells." (PMID 29167450, 2017). "In this investigation, C1QA and C3, the main recognition proteins in complement and coagulation cascade pathways, pertussis pathway, S. aureus infection pathway, and systemic lupus erythematosus pathway, were highly expressed in PDR samples." (PMID 34938191, 2021). "Some researchers believe that VaD may be linked to systemic autoimmune diseases, and through bioinformatics and ML methods, genes such as C1QA, CD163, LY96, and MS4A4A have been identified as potential biomarkers for the link between VaD and systemic lupus erythematosus." (PMID 39116438, 2024).
cognitive decline (6 papers, 2015 to 2025). "In the brain, C1qa expression increase in IBA1+ cells and neurons with age, and C1qa deficiency can mitigate age-related cognitive decline." (PMID 27048300, 2016). "Accumulation of C1q during normal brain aging has been implicated in cognitive decline; age-matched C1qa-deficient mice were observed to perform significantly better in a series of learning and memory behavioral tests compared to WT mice." (PMID 27008854, 2016). "Global deletion of the C1qa gene prevented cognitive decline and the pathologic changes to the cerebrovasculature and white matter found in the brain of obese mice." (PMID 32273396, 2020). "Moreover, age-related cognitive decline in mice is prevented by genetic deletion of C1qa supporting the deleterious effect of this protein and proinflammatory processes in brain function during aging." (PMID 26512759, 2015).
lung carcinoma (6 papers, 2019 to 2025). "More importantly, as a negative or positive regulator of CD93, high sEV-derived miRNA-5193 or C1qA were associated with favorable or unfavorable progression-free survival (PFS) after anti-PD-1 therapy in lung cancer patients." (PMID 38250037, 2024). "In contrast, C1QC+ TAMs expressed the classical TAM-associated genes C1QA, C1QB, C1QC, APOE, and TREM2, which were previously reported in lung cancer." (PMID 37383234, 2023). "We further observed an MDM subset expressing inflammation and phagocytosis-associated genes (cluster 4; CCL18, IL18, C1QA and TREM2) and enriched for samples from patients with COVID-19 pneumonia, as well as samples from patients with lung carcinoma." (PMID 37291214, 2023). "As neutrophils are increasingly recognised as important regulators in lung cancer, we suggest that C1QA–neutrophil interactions may promote the emergence of immunosuppressive TANs, supporting a pro-tumour microenvironment in early-stage LUAD." (PMID 41171372, 2025). "In contrast, TAM-like macrophages expressed a set of genes (APOE, C1QA, C1QB and TREM2), which was found previously to be expressed in the TAMs of lung cancer." (PMID 36466840, 2022).
Stroke (6 papers, 2019 to 2025). Sudden impairment of blood flow to a part of the brain due to occlusion or rupture of an artery to the brain. "Moreover, C1QA has been shown to participate in another important stroke-related process as a risk factor for atherosclerosis." (PMID 34356850, 2021). "The classical pathway, initiated by C1q‐a protein composed of C1QA, C1QB, and C1QC subunits, is a major contributor to stroke‐induced inflammation and vascular injury." (PMID 40842166, 2025). "In contrast, there was no synergistic effect of aging with stroke on C1qa expression, a MG marker gene (data not shown)." (PMID 36824976, 2023). "At 4 weeks post-stroke, the top 10 gene products in the PPI network were Cd44 (degree = 17), C1qb (degree = 15), Fcgr2b (degree = 14), Spp1 (degree = 12), Cd74 (degree = 12), C4a (degree = 12), C1qa (degree = 12), C3 (degree = 10), Cd14 (degree = 10), and Itgb2 (degree = 10)." (PMID 31888302, 2019).
atherosclerosis (5 papers, 2021 to 2025). A disease characterized by the build-up of fatty material and calcium deposition in the arterial wall resulting in partial or complete occlusion of the arterial lumen. "Finally, the C1QB and C1QA genes regulate the development of atherosclerosis by activating the complement system." (PMID 41348730, 2025). "A bioinformatic analysis and machine learning algorithms approach illustrated that 5 hub genes (SPI1, MMP9, C1QA, CX3CR1, MNDA) could predict the risk of atherosclerosis in SLE." (PMID 40725777, 2025). "C1QA has been recognised as a mediator of atherosclerosis progression." (PMID 34356850, 2021).
ovarian carcinoma (5 papers, 2020 to 2024). A malignant neoplasm originating from the surface ovarian epithelium. "TYROBP, ITGB2, C1QB, C1QA and CD53 in module B have the top connectivity among all DEGs and are considered to have important relationship to immune response in ovarian cancer." (PMID 33987033, 2021). "By PPI network and MCODE module, TYROBP, ITGB2, C1QB, C1QA, CD53 and CD163 have top connectivity among all DEGs and are considered to have important relationship to immune response in ovarian cancer." (PMID 33987033, 2021).
schizophrenia (5 papers, 2011 to 2024). A major psychotic disorder characterized by abnormalities in the perception or expression of reality. "Moreover, increased C1qA, C3, and C4 transcripts were reported to be associated with microglial activation in the midbrain of schizophrenia patients." (PMID 34831151, 2021). "In schizophrenia, the gene expression of complement pathway activators (C1qA) and mediators (C3 or C4) was increased in the midbrain, especially in patients with inflammatory biotypes." (PMID 36845383, 2023). "We show, for the first time, increased gene expression of C1qA, C3, and C4 in the midbrain in schizophrenia in cases previously classified as having a high inflammatory status defined by cytokine gene expression." (PMID 33133060, 2020). "We also found the increased expression of component 4 (C4B) and C1QA and C1QB genes in male schizophrenia patients, which participate in inflammation and have been previously linked to schizophrenia vulnerability; meanwhile, increased C4 expression also prompts microglia-mediated engulfment in mice." (PMID 39068467, 2024). "Here, we hypothesized that activators (C1qA) and/or mediators (C3 or C4) of the classical pathway would be elevated in the midbrain of those with schizophrenia compared to controls, especially in those with a high inflammatory biotype." (PMID 33133060, 2020). "While we found positive correlations between complement transcripts (C1qA and C3) and microglia or astrocyte markers across diagnostic and inflammatory subgroups, the only unique strong positive correlation was between CD163 and C1qA mRNAs in schizophrenia cases with high inflammation." (PMID 33133060, 2020). "However, C1qA mRNA (F = 11.68, df = 50,2, p < 0.0001) was elevated in the high inflammatory/schizophrenia subgroup compared to the control group (98.2%, p ≤ 0.0001) and compared to the low inflammatory/schizophrenia subgroup (128.4%, p < 0.0001)." (PMID 33133060, 2020). "The relationship between gene expression of C1qA and CD163 reflected a pattern distinct to the high inflammatory/schizophrenia subgroup." (PMID 33133060, 2020). "In the present study four SNPs of the complement C1Q component genes (C1QA: rs292001, C1QB rs291982, rs631090, rs913243) were investigated in schizophrenia-affected and healthy subjects." (PMID 21951915, 2011). "In contrast, C1qA mRNA is related to astrocyte and microglia markers in both schizophrenia subgroups irrespective of inflammatory status." (PMID 33133060, 2020). "However, no data regarding association of C1Q encoding genes (C1QA and C1QB) polymorphisms to schizophrenia have been published yet." (PMID 21951915, 2011).
staphylococcus aureus infection (5 papers, 2020 to 2023). An infectious process in which the bacteria Staphylococcus aureus is present. "C1Q3, C1QB, and C1QA were enriched in both the staphylococcus aureus infection, complement, and coagulation cascades pathway." (PMID 33344459, 2020). "The genes C1QA, C1QB, C1QC, C1S, C3, and C4A in cluster 2 were predominantly enriched in top ten pathways including Staphylococcus aureus infection, pertussis and complement and coagulation cascades." (PMID 37409113, 2023).
pancreatic cancer (4 papers, 2021 to 2025). "We visualized changes by UMAP, and found that C1qa, C1qb, and C1qc, immunosuppressive macrophage markers in pancreatic cancer, were upregulated in the ON compared with the OFF group." (PMID 39782689, 2025). "The macrophage 1 population was defined by Apoe, C1qa, and C1qc markers of TAMs in mouse and human pancreatic cancer, while the macrophage 5 population expressed Ear2 and Retnla." (PMID 36727849, 2023). "This study uses biomaterial scaffolds to identify a macrophage gene signature defined by high expression of C1qa, C1qb, and Trem2 that is elevated systemically in mouse and human pancreatic cancer." (PMID 33782087, 2021). "While C1qa, C1qb, and Trem2 are known drivers of alternatively activated macrophage polarization in a LPS-induced inflammation model, little is known about their involvement in pancreatic cancer." (PMID 33782087, 2021). "Finally, we determined that C1QA and C1QB expression is enriched in pancreatic cancer patient blood compared with healthy individuals, suggesting that the elevation of these markers may serve as a novel predictor of disease in PDA patients." (PMID 33782087, 2021). "Paralleling the mouse data, C1QA, C1QB, and TREM2 were up-regulated in macrophages from human pancreatic cancer compared with macrophages from the non-malignant pancreas." (PMID 33782087, 2021).
C1Q deficiency (3 papers, 2021 to 2025). C1q deficiency is a rare disorder associated with recurrent skin lesions, chronic infections, systemic lupus erythematosus (SLE) or SLE-like diseases. "Diseases related to C1qA include immune deficiency caused by C1q deficiency and complement deficiency in classical component pathways." (PMID 34949204, 2021).
colon cancer (3 papers, 2022 to 2024). "C3+ TeMs (M12) and C1QA+ TeMs (M10) were clustered into the same branch, resembling the IL1B+ macro and C1QC+ TAMs identified in colon cancer, respectively." (PMID 37488416, 2023). "We also analyzed the relationship between C1QA, C1QB, C1QC and the survival of colon cancer patients, and the results showed that a high expression of C1QC in colon cancer patients led to a poor prognosis (p < 0.05)." (PMID 35765947, 2022). "However, the apparent relationship between the high expression of C1QA and C1QB and the prognosis of colon cancer patients still needs to be further explored as statistical significance was not reached, which may be due to insufficient sample size." (PMID 35765947, 2022). "Therefore, it is speculated that the expression levels of C1QA, C1QB, and C1QC are closely related to the development of colon cancer." (PMID 35765947, 2022).
diabetes (3 papers, 2013 to 2025). "The complement factors (C1qb, C1qa, Cfh) are also involved in the complement activation classical pathway, but have not changed expression levels due to diabetes in previous studies." (PMID 24199937, 2013).
diffuse large B-cell lymphoma (3 papers, 2022 to 2024). "Studies have shown that METTL3 inhibits the complement pathway by mediating C1qA methylation and enhances resistance to Rituximab, thereby facilitating the progression of diffuse large B-cell lymphoma (DLBCL)." (PMID 38902779, 2024). "Upregulation of C1QA, C1QB, and C1QC in peripheral T-cell lymphoma and upregulation of C1QC in Epstein-Barr Virus-positive diffuse large B-cell lymphoma have been reported previously." (PMID 36873459, 2022).
lupus erythematosus (3 papers, 2011 to 2022). An autoimmune, connective tissue chronic inflammatory disorder affecting the skin, joints, kidneys, lungs, heart, and the peripheral blood cells. "C1QA encodes the A-chain polypeptide of serum complement subcomponent C1q, which is associated with lupus erythematosus and glomerulonephritis." (PMID 33828969, 2021). "C1QA deficiency is associated with lupus erythematosus and glomerulonephritis." (PMID 36642989, 2022). "The functionality of C1QA rs292001 and C1QB rs631090 has been previously shown in lupus erythematosus." (PMID 21951915, 2011).
malaria (3 papers, 2016 to 2025). Malaria is a serious and sometimes fatal disease caused by a parasite that commonly infects a certain type of mosquito which feeds on humans. "The gene Cfp displayed a very similar expression pattern as C1qa, C1qb, and C1qc in response to blood-stage malaria, with a faster increase towards day 4 p.i. after an initial faster decrease on day 1 p.i. in vaccinated mice than in unvaccinated mice." (PMID 40243929, 2025). "Differentially expressed probes form these canonical pathways that were previously shown to play a role in severe malaria pathogenesis were TLR2, TLR4, TLR8, HSPA6, CR1, C1qA, C1qB, C1qC, FOS, and GZMB." (PMID 26961973, 2016). "Notably, complement genes (C1QA, C1QB, C1QC), apoptotic genes (PDL1, PDL2, APOL1, APOL2, FAS), inflammatory caspases (CASP1, CASP5), TLR pathway genes (TLR1, TLR4, TLR5, TLR8), cytokines (IL6, IL10), and granzyme (GZMB) were among the genes upregulated during symptomatic malaria." (PMID 39161730, 2024).
metastatic tumors (3 papers, 2021 to 2025). "We found that myeloid components in human metastatic tumors were mainly composed of monocytes and TAMs, and all three TAM clusters highly expressed lipid-associated TAM markers (APOE, C1QA, and TREM2) and exhibited a pro-tumoral phenotype featured by CD206 (MRC1) expression." (PMID 40394007, 2025).
myocardial infarction (3 papers, 2024 to 2025). Gross necrosis of the myocardium, as a result of interruption of the blood supply to the area, as in coronary thrombosis. "These include C1qa, C1qb, and C1qc, all components of the membrane attack complex, as well as C5ar1, the receptor for the complement anaphylatoxin 5a, which can stimulate immune cells in myocardial infarct models." (PMID 39202335, 2024).
periodontitis (3 papers, 2024 to 2025). An acute or chronic inflammatory process that affects the tissues that surround and support the teeth. "The enriched pathways in the PPI network were also immune-regulation related, which suggested to a certain extent that C1QA played a certain role in immune regulation in periodontitis, and BST2 was a more likely potential periodontitis regulator." (PMID 38919957, 2024). "In our study, C1QB exists in the core ceRNA network in periodontitis differential mRNAs and differential lncRNAs, which can be seen in the existing studies indicating that C1QB and C1QA have a strong reciprocal relationship." (PMID 38919957, 2024). "The identified biomarkers C1QA, CENPK, CENPU, BST2 and LINC01133 provided valuable insight into periodontitis pathology." (PMID 38919957, 2024). "Single-cell sequencing of gingival tissues from periodontitis patients revealed three types of macrophages, including PRDM1 + Macro, NLRP3 + Macro, and C1QA + Macro." (PMID 38689292, 2024). "Compare differences of AD pathway molecules in healthy tissues and periodontitis tissues, including amyloid beta (A4) precursor protein (APP), a key gene in AD, interleukin-1 beta (IL-1β), and complement component 1 (q subcomponent, A chain) (C1QA)." (PMID 41170438, 2025).